GNLY (granulysin)
Description:
Antimicrobial protein that kills intracellular pathogens. Active against a broad range of microbes, including Gram-positive and Gram-negative bacteria, fungi, and parasites. Kills Mycobacterium tuberculosis.
Synonyms: LAG2; NKG5; TLA519; LAG-2; D2S69E
Tractability: Antibody: its Gene Ontology location is reachable by antibodies, with high confidence; UniProt places it where antibodies can reach, with medium confidence; UniProt predicts a signal peptide or a membrane-spanning region. PROTAC: ubiquitination databases record sites on it; its protein half-life has been measured.
Gene: Protein-coding gene on chromosome 2 (85,685,175 to 85,698,852, forward strand). Ensembl gene ENSG00000115523.
Subcellular location: Secreted
Pathways (Reactome):
Immune System: Antimicrobial peptides
Gene Ontology:
Molecular function: protein binding
Biological process: antimicrobial humoral immune response mediated by antimicrobial peptide; defense response to bacterium; killing of cells of another organism
Cellular component: cytolytic granule; extracellular region; phagocytic vesicle lumen
Genetic constraint (gnomAD): Loss-of-function variants: 10 observed, 10.82 expected, observed/expected ratio (o/e) 0.92, 90% interval 0.57 to 1.55. The upper end of that interval is the gene's LOEUF score, 1.55, which puts it in group 6 of 6, group 1 being the genes least tolerant of losing a copy. Missense variants: 119 observed, 127.53 expected, observed/expected ratio (o/e) 0.93, 90% interval 0.8 to 1.09. Synonymous variants: 56 observed, 51.92 expected, observed/expected ratio (o/e) 1.08, 90% interval 0.87 to 1.35.
Homologues: Orthologues: chimpanzee GNLY (94% identical), pig GNLY (41% identical), dog GNLY (32% identical).
Diseases named in the same sentence as GNLY in open-access papers:
GNLY is named in the same sentence as 127 diseases in open-access papers, as found by Europe PMC text mining. Sharing a sentence is not in itself a finding about the gene and the disease. The quoted sentences say what the papers report.
COVID-19 (20 papers, 2020 to 2025). A disease caused by infection with severe acute respiratory syndrome coronavirus 2. "Granulysin levels were also lower in LTBI/COVID-19 compared to COVID-19, LTBI, and HD (p<0.05, p<0.01)." (PMID 40458413, 2025). "Our findings revealed an elevated frequency of cytolytic markers such as perforin, CD107a and granulysin upon antigen stimulation in late convalescent COVID-19 individuals." (PMID 35336918, 2022). "Our study also sought to explore the distribution and function of CD4+ T cells expressing cytotoxic molecules such as perforin, granzyme B, CD107a and granulysin in COVID-19 convalescent individuals." (PMID 35336918, 2022). "This high expression was even more apparent when comparing cells within the granulysin+ NK cell cluster between patients with COVID-19 and CAP-flu." (PMID 34424199, 2021). "Gene Ontology enrichment of the genes upregulated in granulysin+ NK cells from patients with COVID-19 exposed a clear type I interferon response." (PMID 34424199, 2021). "The expression of cytotoxic particles (e.g., perforin and granulysin) in CD8 + T cells was demonstrated in an autopsy report of COVID-19 patients." (PMID 32733921, 2020). "The levels of serum cytokines such as IL-6, IL-10, perforin, granulysin, sFas, and granzyme B in COVID-19 patients were significantly higher than those in healthy controls." (PMID 33154753, 2020). "However, LTBI/COVID-19 displays lower soluble levels of granzyme B and perforin in culture supernatants and perforin, granulysin, and sFas in plasma compared to COVID-19." (PMID 40458413, 2025). "Th17 cells during COVID-19 are characterized by phenotype typical to tissue resident memory T cells also expressing the genes associated with cytolytic potential (SRGN, GZMB, and GNLY) and cytokine genes encoding IL-21, IL-17F, IL-17A, IFN-γ, and GM-CSF." (PMID 37626620, 2023). "We found that cells from patients who had recovered from severe COVID-19 have significantly higher cytotoxicity gene expression scores (P = 0.00032), with upregulation of GZMK (P = 3.02 × 10−5) and GNLY (P = 1.41 × 10−9) (encoding granzyme K and granulysin, respectively)." (PMID 34853448, 2022). "Furthermore, it has been reported that Perforin, GZMB and Granulysin expression levels were upregulated in the acute phase of mild COVID-19 patients compared to moderate and severe patients." (PMID 36685601, 2022). "whereas those of sFasL and granulysin were lower in severe COVID-19 patients than controls." (PMID 34831404, 2021). "Research has found that, compared to a control group, serum levels of PARC/CCL18 and GNLY (granulysin), as well as IgG levels against MX1 and METTL3, are elevated in patients with AA related to the COVID-19 vaccine." (PMID 39021569, 2024). "COVID-19 patients with encephalopathy had significant overexpression of various cytotoxic genes, including PRF1, GZMK, GZMA, GZMB, GNLY, and CST7." (PMID 37848421, 2023). "In this study, we analyzed the gene expression pattern of cytotoxic proteins (PRF1, GZMB, GNLY, GZMA, GZMK), cytokine (IFN-γ), and apoptotic protein (FASL) in CD8+ T cells from the peripheral blood of COVID-19 patients." (PMID 34945761, 2021). "Patients with mild COVID-19 exhibited expanded subsets of unconventional CD56dimCD16- NK cells with elevated NKG2D expression and lower levels of cytotoxic mediators (granzyme A, granzyme B, and granulysin)." (PMID 40421029, 2025). "Conversely, cytotoxic GNLY-expressing effector cell proportions and mature NK cells (NK_CD16hi) increased in Non-COVID-19, Post-COVID-19 and MIS-C but not in Post-Vaccination." (PMID 39994453, 2025). "Furthermore, there was a trend toward higher mRNA expression of other cytotoxic proteins, GNLY and GZMB, in CD8+ T cells in mild COVID-19 patients with stable clinical appearance." (PMID 34945761, 2021).
COVID-19 (continued). "Performing this analysis for the COVID-19 patients demonstrated clear B- and T-cell clusters, defined by expression of TCF7, LEF1 (clusters 0 and 1), CD74, CD79A (clusters 2 and 3), IL7R (cluster 4) and CCL5, NKG7, GNLY (cluster 6)." (PMID 33884369, 2021). "In line with high GNLY expression in the EMRA-like 2 T cell cluster expanded in CAP-flu, we found a higher proportion of granulysin+ NK cells in CAP-flu, whereas the other (granulysin negative) NK cell cluster was highest in COVID-19." (PMID 34424199, 2021). "Other studies also reported increased PRF1, GNLY, soluble Fas, and GZMB in COVID-19 patients." (PMID 34945761, 2021).
tuberculosis (17 papers, 2009 to 2025). A chronic, recurrent infection caused by the bacterium Mycobacterium tuberculosis. "Human CD8+ cytotoxic T cells expressing the cytotoxic granule proteins granzyme B, perforin, and granulysin have been linked to host defense in leprosy and tuberculosis, with both granulysin and granzyme B having direct antimycobacterial activity." (PMID 40569678, 2025). "While the antigen-independent production of IFN-γ plays an important role in host defense, the cytotoxic mechanisms mediated by perforin, granzymes, and granulysin further increase the immune response against Mtb, highlighting both their protective and potentially pathogenic effects in tuberculosis." (PMID 40825006, 2025). "For example, in patients with active tuberculosis, a progressive loss of effector function of circulating Vγ9Vδ2 T cells has been reported, leading to decreased IFN-γ production and granulysin expression." (PMID 35833118, 2022). "Such a role for granulysin-expressing CD8 T cells would also be consistent with their significant association with granuloma that restrict the growth of M. tuberculosis in the cynomolgus macaque TB model." (PMID 36409085, 2022). "PD-1 blockade is described to increase perforin, granzyme B, and granulysin expression in T-cells of tuberculosis and cancer patients." (PMID 29312350, 2017). "Patients with active tuberculosis (TB) from Indonesia had significantly lower serum granulysin levels compared with healthy controls, and granulysin levels normalized after 2 months of treatment." (PMID 36409085, 2022). "Granulysin produced by cytolytic T cells directly contributes to immune defense against tuberculosis (TB)." (PMID 22216262, 2011). "CD4+ CD45RO+ T cells co-expressing granulysin with specificity for Mycobacterium tuberculosis (Mtb) were present in high frequency in TB-experienced children and adolescents." (PMID 22216262, 2011). "Here, we used GNLY-Tg mice to test the hypothesis that expression of granulysin endows CD8 T cells with a greater capacity to abrogate TB by killing intracellular M. tuberculosis." (PMID 36409085, 2022). "In humans, it has been shown that GNLY expressed in peripheral blood mononuclear cells (PBMC) is a biomarker for childhood and adolescent tuberculosis and for the diagnosis of serious bacterial infections." (PMID 24341289, 2013). "We hypothesized that granulysin-mediated clearance of M. tuberculosis parasited inside and outside of alveolar macrophages in presumptive infected hosts might enhance the chemotherapeutic efficacy on TB." (PMID 32929333, 2020). "Granulysin may act synergistically with perforin and IFN-γ, pointing to its critical importance for the control of tuberculosis." (PMID 32823923, 2020). "Finally, anti-tuberculosis therapy resulted in significantly diminished levels of cathelicidin, HBD2, granulysin and significantly enhanced levels of HNP1-3 and granulysin in PTB-DM and/or PTB individuals." (PMID 28910369, 2017). "GNLY, granulysin; TB-Ag-stimulated interferon-gamma values, tuberculosis antigen values minus negative-control values in the blood." (PMID 27756230, 2016). "Constitutive expression of perforin and granulysin by cord blood NK-cells likely provides innate immunity, while BCG vaccination-induced expression of these cytolytic mediators may contribute towards protection of the neonate against tuberculosis." (PMID 21234358, 2011). "Interestingly, culture supernatants containing the granulysin, successfully secreted by rAdhGLs-treated U937 or RAW264.7 cells, had a clear dose-dependent growth inhibition on M. tuberculosis H37Rv or MDR-TB strains." (PMID 32929333, 2020). "Furthermore, in individuals with active tuberculosis and comorbidities such as diabetes mellitus (DM), elevated levels of HNP1-3, HBD2, and LL37, along with decreased levels of granulysin, were observed compared to individuals without DM." (PMID 39340094, 2024).
malaria (12 papers, 2015 to 2023). Malaria is a serious and sometimes fatal disease caused by a parasite that commonly infects a certain type of mosquito which feeds on humans. "Interestingly, we could detect the release of granulysin upon cancer cell recognition—this has previously only been associated with γδ T cell-mediated disease control of malaria and tuberculosis infections." (PMID 32983105, 2020). "Consisted with us, γδT cells have been shown to provide immune protection against blood-stage malaria in a granzyme and granulysin mediated innate immune mechanism." (PMID 35127555, 2021). "Here, we show that CTLs and GNLY mediate mouse resistance to blood-stage infection with P. yoelii, a rodent malaria parasite that preferably infects reticulocytes." (PMID 32913355, 2020). "The potential importance of CD8+ T cells during blood stage malaria, was also recently highlighted in Py (17XNL1.1)-infected transgenic mice expressing the human-restricted cytolytic effector molecule granulysin (GNLY)." (PMID 33519801, 2020). "In malaria patients, high levels of granulysin-expressing Vγ9Vδ2 T cells correlate with their ex vivo parasite-specific degranulation capacity, and elevated granulysin concentration in plasma suggests significant discharge during acute P. falciparum malaria." (PMID 26169273, 2015). "Furthermore, adult Vγ9Vδ2 T cells, which are expanded in the blood stage of malaria-infected patients (Plasmodium falciparum), are able to reduce parasite reinvasion in a granulysin-dependent manner." (PMID 34255746, 2021). "Notably, CD16+ Vδ2 T cells from malaria-exposed individuals phenotypically resemble mature NK cells, including expression of the cytolytic effector molecules perforin, granzyme B and granulysin, as well as CX3CR1 and KIRs, and down-regulation of IL18R." (PMID 33085728, 2020). "Our results indicate that CTL-mediated resistance to blood-stage malaria requires IFN-γ-dependent expression of MHC-I on iRetics and is partially mediated by GNLY." (PMID 32913355, 2020). "The immunity related genes that are down-regulated in the malaria severity signature are: PRF1, GNLY, OAS2, MX1, OAS3 and CCL5." (PMID 29642892, 2018). "Similarly, in malaria these genes were either only modestly upregulated (GZMA and GZMB) or were downregulated (GZMH, GNLY and PRF1), compared to HS (P < .05)." (PMID 33793565, 2021). "The rodents in all of these studies did not express GNLY, which limits their usefulness for understanding protective immunity in human malaria." (PMID 32913355, 2020). "Although we have not examined parasite survival, mouse malaria may not be the same as human, as malaria infection does not induce granulysin expression in mice." (PMID 31608052, 2019). "Granulysin (but not perforin) released through cytotoxic granules also appears to be required for anti-parasitic activity, which is supported by the existence of granulysin-expressing Vγ9Vδ2 cells in patients with malaria." (PMID 30405634, 2018).
colorectal cancer (8 papers, 2004 to 2026). A primary or metastatic malignant neoplasm that affects the colon or rectum. "Studies have confirmed that CD8+ T cell infiltration is associated with a good prognosis in triple-negative breast cancer, and high mRNA expression of GNLY and GZMB in tumors is associated with a good prognosis in colorectal cancer." (PMID 40860340, 2025). "One study showed that upregulated mRNA expression of intratumoral GNLY and GZMB was associated with a favorable outcome in patients with colorectal cancer." (PMID 39643914, 2024). "Granzyme A and granulysin were found to be upregulated in MSI-H colorectal cancers as compared with MSS cancers, indicating the immune mediators involved in cytotoxic lymphocyte functions are upregulated and the cells in the tumor are likely to be activated." (PMID 20631828, 2010). "Such a response might be mediated by Natural Killer cells that characteristically release Granulysin to induce tumour cell death, a recognised feature of MSI-H colorectal cancer, which in turn releases intra-cellular TSA's." (PMID 15298707, 2004).
psoriasis (8 papers, 2020 to 2025). An autoimmune condition characterized by red, well-delineated plaques with silvery scales that are usually on the extensor surfaces and scalp. "Interestingly, genetic analyses suggest a relationship between GNLY polymorphisms and psoriasis." (PMID 32917058, 2020). "But GNLY has been found to play an important role in infection and immune-related diseases, such as osteoarthritis, psoriasis and chronic viral hepatitis." (PMID 37898694, 2023). "In addition, GNLY+ T cells were recently detected in the psoriatic plaques and peripheral blood of patients with psoriasis, and the frequency of these cells correlated with the severity of the disease." (PMID 39020008, 2024). "The frequency of GNLY+ NK cells is increased in the peripheral blood of psoriasis patients." (PMID 32917058, 2020). "Specifically, through supplementary validation of gene expression using the psoriasis dataset, the distinctively high expression characteristics of CXCL13 and GNLY in DLE were revealed, thereby corroborating their central status as characteristic markers of DLE." (PMID 41214060, 2025). "GNLY is a cytolytic antimicrobial peptide (AMP) released from the granules of both cytotoxic T lymphocytes (CTLs) and natural killer (NK) cells, which mainly involved in the occurrence of psoriasis." (PMID 36199375, 2022).
melanoma (7 papers, 2019 to 2025). A malignant, usually aggressive tumor composed of atypical, neoplastic melanocytes. "In this study, two populations of NK cells were identified: NKCyto (which compared with NK cells from OT metastatic melanoma lesions from NRs, expressing GNLY, CXC3R1, and FCGR3A) and NKRest (expressing XCL1 and XCL2)." (PMID 40530504, 2025). "By combiningγδ-T exosomes and PDT, we achieved a robustantitumor effect from γδ-T exosome-derived cytolytic molecules,including granzyme A, granzyme B, perforin, and granulysin, and Ce6-mediatedROS generation inside melanoma cells." (PMID 39862206, 2025). "However, this would not cause resistance in our mouse melanoma because murine CD8 T cells lack granulysin." (PMID 39281881, 2024). "A recent study found that NKG7 and GNLY were overexpressed in patients that responded to anti-PD-1 and CTLA-4 in malignant melanoma." (PMID 33804039, 2021). "ccRCC and melanoma shared three genes that correlate to CD40 (OASL, GNLY, and IFI35)." (PMID 33804039, 2021).
lung carcinoma (6 papers, 2017 to 2024). "The effects of three flavonoids, namely apigenin, luteolin, and quercetin, on NK cell activity against lung cancer cells, and on the secretions of the cytotoxic granules perforin and granulysin were also examined." (PMID 36982245, 2023). "Furthermore, previous study documented that Apigenin and luteolin (12.5 μg/ml and 25 μg/ml) exhibited ability to raised NK cells cytotoxicity on lung cancer cells via elevated expression of perforin and granulysin." (PMID 39619199, 2024).